CXCL12 (C-X-C motif chemokine ligand 12)
Diseases named in the same sentence as CXCL12 in open-access papers (continued):
Sharing a sentence is not in itself a finding about the gene and the disease.
tumor (continued). "In addition, immunohistochemistry analysis showed that the highest expression of CXCL12 in stromal fibroblasts and the least levels of TGF-β in iCCA cells are found at the invasive front of the tumor, probably favoring CCA invasion." (PMID 32784743, 2020). "Furthermore, CCL19/CCR7, CXCL12/CXCR4, and CCL20/CCR6 were shown to be potential new targets for tumor gene therapy in type 2 PRCC." (PMID 32775427, 2020). "CXCL12 and CCL20 were shown to be stimulatory chemokines related to tumor neovascularization." (PMID 32775427, 2020). "Chemokines and their receptors play an important role in directing cognate T-APC interactions in lymph nodes and spleen (e.g., CCR7 and CCL21/19), or in bone marrow (e.g., CXCR4 and CXCL12 (SDF-1α/β), or attracting Treg cells towards tumor tissue (e.g., CCR2 and CCL2 (MCP-1))." (PMID 32155856, 2020). "As with the tumor itself, TME also responds to RT by inducing the release of pro-inflammatory cytokines and other molecules, including PDGF, IL1β, TNFα, TGFβ, C-X-C motif chemokine 12 (CXCL12), MMPs, IL6, EGF, and VEGF." (PMID 32660072, 2020). "In addition, CXCL12 attracts immunosuppressive innate immune cells, mostly Ly6Clow monocytes and Ly6G+ neutrophils which predominantly express CXCR4 in the tumor microenvironment." (PMID 33096815, 2020). "Whereas the tumorigenic functions of CAF-S2 and S3 have not been defined, CAF-S1 and CAF-S4 secrete TGF-β and CXCL12 that activate NOTCH signaling in tumor cells, promoting proliferation and invasion." (PMID 33114328, 2020). "Moreover, as activation of the CXCL12/CXCR4 axis stimulates VEGF and MMP production in mature endothelial cells, CXCR4 antagonists also inhibit tumor angiogenesis in animal models of human tumors." (PMID 32528888, 2020). "Interestingly, most deregulated genes, such as IL6, RelB, RelA, Plac8, ITGA5, CXCL12 and FN1, among other cytokines and growth factors, have been involved in tumor growth and progression." (PMID 32848147, 2020). "Although CXCR4 expression is a prognostic factor in several human tumor types, none of the CXCL12/CXCR4/CXCR7 has yet been definitively validated as a tumor driver." (PMID 33363463, 2020). "In addition, widely studied CAF-derived proinflammatory cytokines influencing tumor growth and invasion include the CXC-chemokine ligand 12 (CXCL12)." (PMID 32466591, 2020). "CXCL12, together with its C-X-C motif receptor 4 (CXCR4), which is overexpressed in malignant cells, plays an important role in the development of BMs, because its activation promotes tumor cell proliferation and angiogenesis." (PMID 31500357, 2019). "And they can modify TME that subsequently leads to tumour cell proliferation by producing proangiogenic factors (CXC12, VEGF, FGF, IL8/CXCL8, and PDGF-C), CCL-2, IL-6, FAP, IL-4, hyaluronan, IL-8, CXCL9, CXCL10, CXCL12, and Fsp1." (PMID 30944831, 2019). "FAP-positive CAFs in tumor stroma are the major source of C-X-C motif ligand 12 (CXCL12) in the tumor, and inhibition of its receptor, the C-X-C motif receptor 4 (CXCR4), induced T cell accumulation in the tumor and acted synergistically with anti-PD-L1 in diminishing cancer cells." (PMID 31540286, 2019). "Considering the detection sensitivity of the applied analytical method, no other MMPs, CXCL12, and CXCR4, associated or overexpressed in tumor recurrence, were found in the AC solid tissues analyzed." (PMID 31191748, 2019). "IR reduces vascular diameter, activating hypoxia-inducible factor 1α (HIF1α) and vascular endothelial growth factor (VEGF), provoking the release of chemokine (C-X-C motif) ligand 12 (CXCL12), which altogether protect tumour cells from cellular stress and death." (PMID 30764513, 2019). "Through secreting CXCL12, geminin-overexpressing cells recruit these CXCR4+-MSCs into the tumor." (PMID 31844158, 2019).
tumor (continued). "These small-restricted areas around capillaries and pericytes topically overlap with hematopoietic progenitor cell niche and are characterized by C-X-C motif chemokine 12 (CXCL12) expression, whose receptor CXCR4 is frequently overexpressed on primary tumor cells." (PMID 31159336, 2019). "A similar mechanism is mediated by tumor-expressed CXCR4 and CXCL12 expressed in LECs and LNs." (PMID 31105685, 2019). "Furthermore, production of PGE2 by MDSC stimulates the expression of C-X-C chemokine receptor type 4 (CXCR4) and Stromal cell-derived factor 1 (CXCL12) responsiveness, facilitating the migration of MDSC into sites of inflammation and tumor." (PMID 31275327, 2019). "In addition, the secretion of CXCL12 by PSCs results in limiting the migration of CD8+ T cells to juxtatumoral stromal compartments, protecting the tumor cells from the cytotoxicity of CD8+ T cells." (PMID 30987642, 2019). "CXCL12 also stimulates proliferation and survival of CXCR4 positive tumor cells." (PMID 31248118, 2019). "CXCL12 and CCL2 can promote angiogenesis and inhibit apoptosis of endothelial cells by directly binding their receptor (CXCR4 and CCR2, respectively) expressed on tumor vessels or indirectly promoting the recruitment of leukocytes." (PMID 30894861, 2019). "This response could be attributed to the binding of environmental CXCL12 to CXCR4 on CLL B cells and the subsequent activation of the AKT/FoxO3a/Bim axis within tumor cells." (PMID 30927928, 2019). "Macrophages may differentiate from cells in the tumor microenvironment or be recruited via CCL2, CCL5, and CXCL12." (PMID 30931508, 2019). "Persistent tumor release of growth factors and cytokines (such as G-CSF, GM-CSF, and VEGF), promote MDSC production in the BM, whereas tumor release of chemokines (i.e., CCL2, CXCL12) recruits them within the tumor microenvironment (TME)." (PMID 31281314, 2019). "Univariate modelling determined that 5T4 expression (p = 0.006), CXCL12 expression (p = 0.026), adjuvant therapy (p = 0.003), FIGO staging (p < 0.001), tumour grade (p = 0.001) and histotype (p < 0.001) were significantly associated with cancer-specific survival in this cohort." (PMID 31332693, 2019). "As TCF12 regulated CXCR4 and CXCL12 expression, an in vitro HUVECs tube formation assay was conducted to explore whether TCF12 plays a functional role in tumor angiogenesis." (PMID 31534521, 2019). "Some cytokines, chemokines or growth factors such as tumor growth factor-β (TGF-β), the chemokine C-C motif ligand 2 (CCL2), colony-stimulating factor 1 (CSF-1), C-X-C motif chemokine ligand 12 (CXCL12), or insulin-like growth factor 1 (IRF1) are induced by RT in the tumor environment." (PMID 31179236, 2019). "We showed that both chemokines (CXCL12, IP-10, and CCL27) and cytokines profiles (IL-1β and IL-6) were altered in the tumor microenvironment and might reduce NK cell function and recruitment to the tumor site." (PMID 31105699, 2019). "Notably, the tumor stromal compartment can, in turn, modulate chemokine activity, as for CXCL7/NAP-2 and CXCL12." (PMID 30591657, 2018). "Moreover, CXCL12 produced within the tumor can attract CXCR4+ Treg, MDSC and plasmacytoid dendritic cells (pDC), potentiating the tumor-promoting effect." (PMID 30319622, 2018). "CXCL12 and CXCR4 have been identified with significantly elevated levels in various malignancies and correlate with the survival, proliferation, angiogenesis, and the metastasis of tumour cells." (PMID 29887884, 2018). "Next, we aimed to understand whether tumor expression of CXCR4 and CXCL12 may significantly contribute to serum CXCL12 levels." (PMID 30012106, 2018). "TNFα released by tumor cells and cells of TME acts through its receptor TNFR1 and further reinforces TNFα expression and the inflammatory and immune-modulatory network including CXCL12, CCL2, IL-6, VEGF, and macrophage inhibitory factor." (PMID 30154786, 2018).
tumor (continued). "However, its specific role is still a controversial issue, probably due to the tumor heterogeneity but also because of the different techniques, methodologies and protocols used in quantification of CXCR4 and CXCL12 expression." (PMID 30012106, 2018). "During cancer development, macrophages are recruited in the tumor stroma by several inflammatory mediators, such as chemokines: CCL2 (also known as MCP-1), CCL5, CXCL12 (also known as SDF-1), cytokines: vascular endothelial growth factor (VEGF), CSF1, and activated complement elements." (PMID 29675018, 2018). "Together, these studies strongly suggest that tumor cells may indeed benefit from an autocrine CXCL12/CXCR4 loop in the tumor microenvironment and that high CXCL12 expression in lymph nodes may indeed promote the metastasis of CXCR4 expressing cells." (PMID 30257500, 2018). "Also, the interaction between CXCL12 and CXCR7 did influence CXCR4-mediated trans-endothelial migration of human tumor cells." (PMID 29977203, 2018). "Mammalian CXCL12/CXCR4 signaling is involved in many cellular programs ranging from directed cell migration and organ development to self-renewal of hematopoietic stem cells and tumor metastasis." (PMID 30202007, 2018). "Lymph endothelial cells secrete chemokines including chemokine (C-X-C motif) ligand 12 (CXCL12) and chemokine (C-C motif) ligand 21 (CCL21) to recruit tumor cells that express chemokine (C-C motif) receptor 7 (CCR7) and chemokine (C-X-C motif) receptor 4 (CXCR4)." (PMID 29805773, 2018). "In addition, CXCL12-dependent stimulation of CXCR4 on tumor cells has been shown to activate key downstream pathways including PI3K/AKT/mTOR and ERK1/2, which promote tumor cell survival proliferation, migration, and angiogenesis." (PMID 30257500, 2018). "NOX-A12, a Spiegelmer developed by Noxxon Pharma® (Berlin, Germany) is a 45 nt-long aptamer that blocks the stroma cell-derived factor (SDF-1) or also known as CXCL12, a chemokine which promotes stem cell migration to the bone marrow enabling vasculogenesis, tumor growth, and metastasis." (PMID 30340426, 2018). "CXCL9 and CXCL12 can form heterocomplexes, and in PCNSL are coexpressed on the tumor vasculature." (PMID 30319638, 2018). "Their recruitment to the tumor sites is mediated by the CXCL12/CXCR4 axis, and might be enhanced by the chemokines known to form a complex with CXCL12." (PMID 30319638, 2018). "Hypoxia increases CXCL12/CXCR4-mediated adherence of non-small cell lung carcinoma cells to lymphatic endothelial cells, which may serve as a means of tumour metastases." (PMID 30178305, 2018). "Some studies have suggested that both CXCL12 and CXCR4 contributed significantly during angiogenesis and hematopoietic stem cell mobilization, while others have suggested its major contribution during tumour development." (PMID 30060445, 2018). "CXCL12-induced migration is enhanced in CXCR4+/CXCR3+/CD8+ T lymphocytes and in CXCR4+/CXCR3− malignant B cells, indicating that chemotactic cues in the perivascular environment serve as regulators for the recruitment of tumor infiltrating lymphocytes (TILs)." (PMID 30319638, 2018). "The CXCL12 and CXCR4 axis plays a role in the metastatic homing of tumour cells." (PMID 29887884, 2018). "Surprisingly, the anti-CXCL12 antibody failed to suppress tumor growth indicating that inhibition of the CXCL12/CXCR4 axis is not responsible for antitumor activity." (PMID 29682200, 2018). "The stromal cell-derived fractor-1 (SDF-1) or CXCL12/CXCR4 axis, critical for trafficking/homing of hematopoietic stem cells, represents an important functional axis in many solid tumors involved in the mechanism of tumor metastasis." (PMID 29389895, 2018). "Therefore, a positive feedback loop has been suggested where in CXCL12 induced TNF-α potentially acts on the cancer cells and induces CXCR4 expression thereby enhancing tumor cell migration." (PMID 30061485, 2018).
tumor (continued). "CXCL12 may serve to prevent adequate T and CAR-T cell penetration into or recognition of the tumor by forming a barrier of CXCR4+ immunosuppressive cells." (PMID 30420856, 2018). "Partial toxin‐induced depletion of FAP+ CAFs, as well as pharmacological blockage of CXCL12 signaling by inhibiting its receptor C‐X‐C chemokine receptor 4 (CXCR4), reduced tumor growth and enhanced T cell accumulation within the tumor, thus sensitizing tumors to α‐PDL1 treatment." (PMID 29280568, 2018). "The targets of aptamers actually in clinical trials are extracellular proteins (VEGF165, C5, PDGFβ, coagulation factor IXa, A1 domain of von Willebrand factor, thrombin, TFPI, CXCL12, CCL2, hepcidin peptide hormone), except nucleolin which is highly expressed at the surface of several tumor cells." (PMID 28635657, 2017). "This process is driven by increased tumor hypoxia that manifests in stabilization of HIF-1α and HIF-1β heterodimer (hypoxia-inducible factor 1) and upregulation of SDF-1 (stromal cell-derived factor 1 or CXCL12)." (PMID 28325958, 2017). "Importantly, miR-125b was upregulated by the activation of CXCL12/CXCR4 axis, and then miR-125b in turn enhanced the expression of CXCR4, which forms a positive feedback loop in triggering tumor invasion and progression." (PMID 28176874, 2017). "Additionally, based on gene expression profiles, we revealed abnormalities in cytokines that have been reported to enhance tumor formation and progression (for example, CCL5, CXCL8 and CXCL12)." (PMID 28846080, 2017). "Elevated ERCC1 (HR = 2.1, 95% CI: 1.1–3.9), DKK1, CXCL12, long non-coding RNA MALAT-1 (OR = 3.65, 95% CI: 1.86–7.18) in tissue sample, and detection of circulating tumor cells (pooled HR: 2.36, 95% CI 1.41–3.96) in peripheral blood were risky factors for patients survival." (PMID 29340021, 2017). "Yet, our work also predicts that tumor regions with low numbers of CXCL12-secreting cells and high numbers of CXCR7+ cells in the bulk tumor tissue, even in the presence of endothelial CXCR7+ cells, can allow the formation of gradients pointing into the vasculature." (PMID 29117251, 2017). "By studying CXCL12 gradient dynamics in a relevant, in vivo-like setting computationally, we can learn the major drivers of gradient formation, in particular the roles that CXCL12 isoforms, endothelial CXCR7, tumor composition, and circadian rhythms play." (PMID 29117251, 2017). "CXCL12 was upregulated in normoxic conditions in vitro after paracrine exposure of neuronal and endothelial cells to VEGF secreted by the nearby perivascular fibroblasts and by tumour cells in an autocrine manner." (PMID 29113105, 2017). "Chemokine CXCL12, also known as stromal-cell derived factor 1 (SDF-1), directs leucocyte migration and, through interactions with its receptor CXCR4, it is also involved in the regulation of metastatic behaviour of certain tumour cell lines." (PMID 28280748, 2017). "There is also a study showing that CXCL12 and CXR4 may play significant roles in the metastasis of HCC by promoting the migration of tumor cells." (PMID 28302149, 2017). "As the blood level increases, the secretion rate in the tumor also increases, and the gradient does not reverse because both the blood and tissue are gaining CXCL12 simultaneously." (PMID 29117251, 2017). "Paradoxically, our data suggest that ionizing irradiation may induce multiple resistance mechanisms that could facilitate tumor relapse, e.g. via enhancing CXCL12 and also CD274/CD279 (PD-L1/PD-1) signaling, thus limiting anti-tumor immunity." (PMID 28423491, 2017). "Furthermore, the CXCL12/CXCR4/CXCR7 axis has been implemented in carcinogenesis and tumor progression." (PMID 28445977, 2017). "Mechanistic studies implied that E5 can inhibit the expression of CXCR4 to block the CXCL12-mediated recruitment of endothelial progenitor cells and repress CXCR4 downstream of the Akt and Erk signaling pathway, which are involved in tumor angiogenesis and progression." (PMID 29263923, 2017).
tumor (continued). "CXCL12/CXCR4 is overexpressed by tumour cells, but not by murine stromal peritumoral cells which only produce CXCR4." (PMID 28386296, 2017). "Immunohistochemistry did not indicate CXCL12 expression in the tumor cell areas in the control group, whereas CXCL12 expression was patchy when re-expressed in the tumor cells of the VPA-treated group (arrows)." (PMID 28418886, 2017). "Moreover, blocking of CXCR4, the chemokine receptor for CXCL12, and neutralization of CXCL16, the ligand for CXCR6 in patient-specific cancer cells significantly prevented the migration of cancer cells to the tumor microenvironment (TME)." (PMID 28649646, 2017). "Numerous cell types influence macrophage function including the tumor cells themselves, which not only recruit macrophages to both primary and metastatic tumor sites by secreting chemokines such as CCL2, CCL5 and CXCL12, but also differentiate and polarize them to a tumor-promoting phenotype." (PMID 28881599, 2017). "As expected, CXCL12 expression was almost absent in the tumor cells of the untreated mice while we observed that CXCL12 expression was restored in the residual tumor cells after VPA treatment." (PMID 28418886, 2017). "In summary, our study showed that cell adhesion molecules and the CXCL12/CXCR4 chemokine system is not involved in the PT-induced interaction of tumor cells with the endothelium." (PMID 29100413, 2017). "We conclude that the effects of PT on the interaction of endothelial and tumor cells in vitro are based neither on an influence on cell adhesion molecules nor on the CXCL12/CXCR4 system." (PMID 29100413, 2017). "The chemokine CXCL12 is constitutively secreted by bone marrow stroma cells in CLL and binds CXCR4 on the surface of CLL cells to direct chemotaxis, support tumor survival, and activate various signaling pathways, including STAT3 by phosphorylation of its serine 727 residue." (PMID 29379494, 2017). "Because CXCL12 is the target molecule of HIF-1α, the hypoxic condition resulting from bevacizumab treatment could lead the tumor cells to produce CXCL12, which would in turn prompt the CXCR4+ cells to migrate into the tumor." (PMID 29286323, 2017). "It has been reported that high CXCL12 levels in the tumor may attract CXCR4-positive vascular and inflammatory cells that, once within the tumor, secrete tumor promoting cytokines as well as growth and pro-angiogenic factors." (PMID 27015814, 2016). "In addition, the lymphatic endothelial cells produce chemokines such as the stromal-derived factor 1 (or CXCL12), which bind CXCR4 receptors in the tumor cells, facilitating their migration toward the lymphatic vessel." (PMID 27806339, 2016). "The serum concentrations of CXCL12 and CXCR4 and classical tumor markers such as carcinoembryonal antigen (CEA) and squamous cell cancer antigen (SCC-Ag) were measured using immunoenzyme assays, while C-reactive protein (CRP) levels were assessed by immunoturbidimetric method." (PMID 27041792, 2016). "In our present paper, the serum concentrations of CXCL12 were significantly higher, while CXCR4 was significantly lower in EC patients compared to healthy controls, while the levels of classical tumor markers as well as CRP were found to be also higher in EC patients than in control group." (PMID 27041792, 2016). "Using the zebrafish model, we propose that receptor activation via ligand stimulation and not necessarily in response to a Cxcl12 gradient enhance tumor burden and subsequent invasion." (PMID 26744352, 2016). "Stromal cells release CXCL12 and attract CXCR4-expressing tumor cells to the new microenvironment." (PMID 27835905, 2016). "Third, AMD3100 inhibits the tumor growth of ESCC expressing CXCL12 in vivo, which has not been previously reported." (PMID 27439769, 2016).